NEAT1 (nuclear paraspeckle assembly transcript 1)
Diseases named in the same sentence as NEAT1 in open-access papers (continued):
Sharing a sentence is not in itself a finding about the gene and the disease.
multiple sclerosis (6 papers, 2019 to 2024). A progressive autoimmune disorder affecting the central nervous system resulting in demyelination. "A screening of 84 lncRNAs revealed an upregulation of NEAT1 in the serum of patients suffering from multiple sclerosis (MS) compared to either healthy controls or patients with who have idiopathic inflammatory myopathy (IIM)." (PMID 30717168, 2019).
osteoporosis (6 papers, 2022 to 2024). A condition of reduced bone mass, with decreased cortical thickness and a decrease in the number and size of the trabeculae of cancellous bone (but normal chemical composition), resulting in increased fracture incidence. "Unloading-induced bone loss or osteoporosis may be eliminated by upregulating the Neat1 level or stabilizing the paraspeckle structures through exercise and mechanical loading in combination with specific small molecules and oligonucleotides." (PMID 35210394, 2022). "The study also demonstrated that the knockdown of NEAT1 led to decreased bone mass and increased bone resorption in an ovariectomized mouse model of osteoporosis." (PMID 39156986, 2024). "An analysis of the ceRNA network has unveiled that NEAT1/MALAT1-hsa-miR-32-3p-SP1/FZD6 and NEAT1/MALAT1-hsa-miR-22-3p-PTEN/ESR1/ERBB3/CSF1R/CDK6 are likely pivotal contributors to the pathogenesis of osteoporosis." (PMID 37814309, 2023). "Studies have shown that NEAT1 promotes the proliferation and differentiation of osteoblasts and, regulates the development and progression of osteoporosis." (PMID 37600656, 2023). "To detect the potential role of Neat1 and paraspeckles in osteoblast function, we determined the Neat1 and Neat1_2 expression levels in bone tissue from mice with hindlimb unloading/loading and patients with osteoporosis." (PMID 35210394, 2022). "The authors suggest that Neat1 may be a potential therapeutic target for treating bone-related diseases such as osteoporosis." (PMID 39156986, 2024). "Moreover, considering the effect of NEAT1 on upregulated osteoclastic and adipogenic differentiation and decreased osteogenic capability, the application of si-NEAT1 to the bone marrow microenvironment might represent a new approach for the treatment of age-associated osteoporosis." (PMID 34497381, 2022). "NEAT1 and SNHG1 are thus promising targets for the treatment of osteoporosis." (PMID 37600656, 2023). "We constructed the NEAT1-hsa-miR-128-3p-IL17RA and SNHG1-hsa-miR-128-3p-IL17RA networks to provide a theoretical basis for understanding the molecular mechanisms of IL17RA involvement in osteoporosis." (PMID 37600656, 2023). "In patients with clinical osteoporosis, total NEAT1 and NEAT1_2 levels in human bone specimens were substantially reduced compared with those in the controls without osteoporosis, and their levels were positively correlated with the T score in the samples of the patients with osteoporosis." (PMID 35210394, 2022).
Stroke (6 papers, 2020 to 2024). Sudden impairment of blood flow to a part of the brain due to occlusion or rupture of an artery to the brain. "Induction of OGD/R or stroke results in an increased expression of NEAT1, which is associated with enhanced LD formation and elevated expression levels of autophagy-related genes." (PMID 38212456, 2024). "The present study analyzed the role of the lncRNA NEAT1 and its underlying mechanisms under both in vitro and in vivo stroke conditions, thus establishing NEAT1 as a possible target for future stroke treatment." (PMID 38212456, 2024). "The present study therefore sheds new light into the complex signaling machine of NEAT1 under stroke conditions." (PMID 38212456, 2024). "On the contrary, downregulation of NEAT1 protects neurons against apoptosis in preclinical stroke settings, significantly inhibiting M1 polarization of microglia." (PMID 38212456, 2024). "Treatment with ASO NEAT1, however, reversed the stroke-induced deficits on motor coordination at 7 dpi." (PMID 38212456, 2024). "Under such preclinical stroke conditions, NEAT1 can also function as a miRNA sponge to modulate the inflammatory response generated upon induction of the noxious stimulus through the miR‐374a‐5p/NFAT5 signaling pathway." (PMID 38212456, 2024). "NEAT1 is a key player of LD agglomeration and autophagy stimulation, and NEAT1 knockdown provides a promising therapeutic value against stroke." (PMID 38212456, 2024). "The present study analyzed the role of NEAT1 under stroke conditions through a series of in vitro and in vivo experiments." (PMID 38212456, 2024). "In our preclinical stroke model, these markers were significantly increased, whereas silencing of NEAT1 significantly reduced the expression of these autophagy-related markers." (PMID 38212456, 2024). "Regulating NEAT1 under hypoxic or ischemic brain conditions proved to be a vital signaling pathway, since knockdown of NEAT1 in mice not only reduced LD formation and autophagy activity but also resulted in better post-stroke neurological recovery." (PMID 38212456, 2024). "For the first time, the findings presented here suggest that the NEAT1, HOTAIR, and GAS5 are novel diagnostic and prognostic markers for stroke associated with hypertension." (PMID 36439973, 2023). "The precise mechanisms by which NEAT1 may interfere with the pathophysiology of stroke still remain elusive." (PMID 38212456, 2024). "In addition, NEAT1 downregulation significantly upregulated the expression of TREM2 in stroke animals." (PMID 38212456, 2024). "Although the precise mechanisms as to how LD formation is involved in the stroke pathology remain elusive, some information may be drawn from the known interplay between NEAT1 and autophagy." (PMID 38212456, 2024). "Despite this information available, evidence regarding the precise role of NEAT1 under stroke conditions and its interrelationship with LD formation and autophagy activation in stroke remains unclear." (PMID 38212456, 2024). "Hence, further studies were done using 7 dpi as the peak of LD agglomeration in order to study the effect of NEAT1 under stroke conditions." (PMID 38212456, 2024). "Overexpression of NEAT1 exacerbates brain injury in stroke rats." (PMID 38212456, 2024). "Under in vivo conditions, NEAT1 was significantly increased in mice at 24 h post-stroke." (PMID 38212456, 2024). "Furthermore, our in vivo experiment has confirmed that knocking down NEAT1 can ameliorate post-stroke LD agglomeration and cortical cerebral blood flow." (PMID 38212456, 2024). "Furthermore, NEAT1 expression was positively correlated with stroke severity, which was evaluated based on National Institute of Health Stroke Scale (NIHSS) scores and infarct volume." (PMID 33184298, 2020). "Furthermore, the post-stroke effect of NEAT1 on autophagy was also studied." (PMID 38212456, 2024). "Interestingly, knockdown of NEAT1 significantly increased cerebral perfusion in stroke animals." (PMID 38212456, 2024).
Stroke (continued). "Thus, increasing NEAT1 in the hypertensive group may imply a protective role against hypertension-induced stroke." (PMID 36439973, 2023). "Lentiviral transfection with NEAT1 overexpression exacerbated cell death in MCAO rats and significantly aggravated neurological impairment after stroke in these studies." (PMID 38212456, 2024). "In a preclinical stroke model, mice received intraventricular injections of ASO NEAT1 or control vectors in order to yield NEAT1 knockdown." (PMID 38212456, 2024). "While most studies in the field have focused on the functional roles of long noncoding RNAs (lncRNAs) NEAT1, GAS5, and HOTAIR in CVS, less attention has been paid to their clinical relevance to stroke incidence and prognosis." (PMID 36439973, 2023). "They found that knockdown of NEAT1 modulates OGD/R injury in CHME5 cells via the miR-374a-5p/NFAT5 axis, thereby inducing microglia migration from M1 to M2 and suppressing inflammatory responses, making it a potential target for stroke therapy." (PMID 36275741, 2022). "The negative correlation of nuclear enriched abundant transcript 1 (NEAT1) lncRNA has been shown in stroke prognosis and recovery with miR-124 and miR-125a, which are identified as inflammatory miRs." (PMID 33049931, 2020). "Hence, we hypothesized whether or not NEAT1 affects lipid metabolism in the form of LD formation under in vitro or in vivo stroke conditions." (PMID 38212456, 2024). "Even though the current research work provides novel insight into the function of NEAT1 under stroke conditions, the administration of ASO NEAT1 before the onset of stroke may, of course, not entirely reflect the clinical stroke settings." (PMID 38212456, 2024).
tuberculosis (6 papers, 2018 to 2024). A chronic, recurrent infection caused by the bacterium Mycobacterium tuberculosis. "Thus, our results indicate that the expression of NEAT1 increased during Mtb infection, and it might be associated with the outcome of tuberculosis." (PMID 30534569, 2018). "In this study, real-time quantitative polymerase chain reaction (qRT-PCR) was performed to detect the expression of NEAT1 in peripheral blood mononuclear cells (PBMCs) of patients with tuberculosis and analyze the association of NEAT1 with the development, progression, and outcome of tuberculosis." (PMID 30534569, 2018). "We demonstrated that the relative expression of NEAT1 (both NEAT1_1 and NEAT1_2) in patients with tuberculosis was higher than that in the control." (PMID 30534569, 2018). "qRT-PCR was performed in this study to detect the expression of NEAT1 in PBMCs of patients with tuberculosis and healthy controls." (PMID 30534569, 2018). "In this work, we aimed to discuss the expression and clinical significance of NEAT1 in tuberculosis patients." (PMID 30534569, 2018). "Therefore, understanding the biological function and molecular mechanism of NEAT1 in tuberculosis would help provide new targets for the diagnosis or treatment of tuberculosis." (PMID 30534569, 2018). "However, the expression of NEAT1 in patients with tuberculosis is still unclear because the research on lncRNA in tuberculosis is still in its initial stage." (PMID 30534569, 2018). "In conclusion, the present study reported that tuberculosis patients had significantly increased the expression of NEAT1 in their PBMCs, and the dynamic change in NEAT1 could reflect the efficacy of antituberculosis treatment." (PMID 30534569, 2018). "In addition, an Mtb-infecting THP-1 human macrophage model was established to further analyze the in vitro effect of NEAT1 on Mtb infection, thereby highlighting the influence and significance of NEAT1 in tuberculosis." (PMID 30534569, 2018). "Studies have demonstrated that lncRNA NEAT1 was highly expressed in pulmonary tuberculosis (TB) and was related to its progression and recovery." (PMID 35465262, 2022). "It was reported that lncRNA NEAT1 (nuclear paraspeckle assembly transcript 1) was highly expressed in PBMCs and granulomatous tissue from TB patients, as well as in M. tuberculosis infected macrophages, and declined gradually with treatment." (PMID 36081510, 2022). "Therefore, NEAT1 might serve as a potential indicator for patient prognosis of tuberculosis." (PMID 30534569, 2018). "Recent study has demonstrated that lncRNA NEAT1 (which has two subtypes: NEAT1_1 and NEAT1_2) nuclear-enriched abundant transcript 1 (NEAT1) is essential in immune regulation, but the expression and clinical significance in tuberculosis are still unclear." (PMID 30534569, 2018). "Furthermore, some ncRNAs have emerged as potential therapeutic targets, some of which include lncRNAs NEAT1, NEAT2 and lnr6RNA, 152742 in tuberculosis; MALAT1, HEAL, SAF, lincRNA-p21, NEAT1, GAS5, NRON, LINC00173 in HIV/AIDS; miRNA-146a in malaria." (PMID 34737736, 2021). "So far, no study to date has reported the role of NEAT1 in tuberculosis." (PMID 30534569, 2018).
abdominal aortic aneurysm (5 papers, 2020 to 2025). Enlargement and ballooning of the vessel that supplies arterial blood to the abdomen, pelvis and legs. "Additionally, miR-4688 targeting TULP3 promotes the formation of abdominal aortic aneurysms through the STAT3/NEAT1/miR-4688/TULP3 axis." (PMID 40282234, 2025). "Moreover, STAT3 may function as one positive feedback regulator that induces the upregulation of NEAT1 as a competing endogenous RNAs (ceRNA) that then facilitates abdominal aortic aneurysm formation by targeting the miR-4688/TULP3 axis." (PMID 33546665, 2021).
acute lymphoblastic leukemia (5 papers, 2020 to 2024). Leukemia with an acute onset, characterized by the presence of lymphoblasts in the bone marrow and the peripheral blood. "Among the discovered carcinogenic lncRNAs, lncRNA nuclear paraspeckle assembly transcript 1 (lncRNA NEAT1) is upregulated and serve as an oncogene during the onset and progression of various hematopoietic malignancies, such as myeloid leukemia and lymphoblastic leukemia." (PMID 32608537, 2020).
Cerebral ischemia (5 papers, 2022 to 2025). Restriction of arterial blood supply to the brain associated with insufficient oxygenation to support the metabolic requirements of the tissue. "Microglia polarization has been shown to be influenced by lncRNA NEAT1, which is increased in the blood of patients after cerebral ischemia." (PMID 41245147, 2025). "Knockdown of lncRNA NEAT1 downregulates microglia activation, reduces neuronal apoptosis and infarct size after cerebral ischemia." (PMID 41245147, 2025). "Previous results also demonstrated that BBR exerts neuroprotective effects via the m6A methyltransferase METTL3, which regulates the NEAT1/miR-377-3p/Nampt axis in mouse astrocytes to ameliorate cerebral ischemia/reperfusion injury." (PMID 40829428, 2025). "Collectively, the present findings show that berberine exerts neuroprotective effects via the m6A methyltransferase METTL3, which regulates the NEAT1/miR-377-3p/Nampt axis in mouse astrocytes to ameliorate cerebral ischemia/reperfusion injury." (PMID 38180752, 2024). "Taken together, our results demonstrate that berberine exerts neuroprotective effects via the m6A methyltransferase METTL3, which regulates the NEAT1/miR-377-3p/Nampt axis in mouse astrocytes to ameliorate cerebral ischemia/reperfusion (I/R) injury." (PMID 38180752, 2024). "Previous work from other groups described a regulatory role of NEAT1 in settings of cerebral ischemia, albeit these studies predominantly remained descriptive." (PMID 38212456, 2024). "(2020) induced OGD/R in vitro to mimic cerebral ischemia-reperfusion injury and found that the lncRNA NEAT1 may inhibit the polarization of microglia toward the M1 phenotype to reduce OGD/R-induced damage and reduce the activity of the AKT/STAT3 pathway." (PMID 36275741, 2022).
coronary artery disease (5 papers, 2020 to 2026). "NEAT1, or Nuclear-enriched abundant transcript 1, is a lncRNA linked to coronary artery disease (CAD)-associated ischemia/reperfusion (I/R) injury." (PMID 40176927, 2024). "Clinically, NEAT1 is significantly upregulated in PBMCs and AS plaques derived from patients with coronary artery disease." (PMID 41268533, 2025). "Our broader analyses implicated NEAT1 in influencing multiple metabolic traits (e.g. serum triglycerides, diagnosis of T2DM and coronary artery disease), that are of potential relevance to patients with NAFLD." (PMID 35474605, 2022).
depression (5 papers, 2020 to 2025). "NEAT1, PCAT1, RMRP, and NKILA are lncRNAs associated with neuropsychiatric phenotypes such as major depressive disorder (MDD), addictive behavior, and substance abuse." (PMID 36005827, 2022). "Several lncRNAs have been functionally characterized in previous research on pain or depression, such as XIST, uc.48+, NEAT1, and NONRATT007487.2 in neuropathic pain and DISC2, BACE1-AS, and BDNF-AS in depression." (PMID 34440578, 2021). "Finally, the levels of lncRNAs VLDLR-AS1, NEAT1, GAS5 and MALAT1 were analyzed for correlation with depression symptoms, measured using the Patient Health Questionnaire-9 (PHQ-9)." (PMID 38338752, 2024). "We conducted a secondary analysis of the psychological symptom burden in the LIMBIC CENC cohort to evaluate whether the levels of the four serum lncRNAs (VLDLR-AS1, MALAT1, NEAT1, GAS5) correlate to symptom burden (such as cognition, memory, depression or PTSD) after rmTBI." (PMID 38338752, 2024).
head and neck squamous cell carcinoma (5 papers, 2018 to 2026). A squamous cell carcinoma that arises from any of the following anatomic sites: lip and oral cavity, nasal cavity, paranasal sinuses, pharynx, larynx, and salivary glands. "Although research on lncRNAs for head and neck squamous cell carcinoma is limited, a recent study has reported few differentially expressed lncRNAs such as HOTAIR, NEAT1, UCA1, and MALAT1, in oral cancers." (PMID 30002503, 2018).
Hyperglycemia (5 papers, 2020 to 2024). An increased concentration of glucose in the blood. "NEAT1 is overexpressed in individuals, and it is highly expressed in hyperglycemia conditions affecting inflammatory pathways." (PMID 38326874, 2024). "Likewise, NEAT1 is a lncRNA which shows its elevated expression in hyperglycemia and has been shown to directly interfere AKT/mTOR signalling pathway." (PMID 34742256, 2021). "Another reported lncRNA is the Nuclear Enriched Abundant Transcript-1 (NEAT1), which is also highly expressed due to hyperglycemia, and NEAT1 interacts with AKT/mTOR pathway." (PMID 32194418, 2020).
laryngeal carcinoma (5 papers, 2019 to 2025). Carcinoma that arises from the laryngeal epithelium. "For example, DLX6-AS1, NEAT1, ZFAS1 and NKILA regulate the progression of laryngeal cancer through different regulatory mechanisms." (PMID 38967843, 2024). "In laryngeal cancer, several lncRNAs, such as ZFAS1, AFAP1-AS1, and NEAT1, have been shown to be key players in malignant progression." (PMID 38967843, 2024). "Several recent studies have reported that multiple lncRNAs are involved in the progression of head and neck cancer; for example, H19, NEAT1, and HOTAIR are overexpressed in laryngeal cancer." (PMID 32039035, 2019). "Meanwhile, there was a prominently negative correlation between NEAT1 and miR-524-5p expression in laryngeal cancer tissues by Spearman’s correlation analysis (R2=0.6044, P=0.0011)." (PMID 34837887, 2021).
lung squamous cell carcinoma (5 papers, 2019 to 2023). "Neat1 has been shown to sponge miR-214-5p to reduce LTF expression, thus promoting autophagy in lung squamous cell carcinoma cells." (PMID 37716986, 2023). "Of the three lncRNAs, NEAT1 (Nuclear Paraspeckle Assembly Transcript 1), which is known for its oncogenic role in many cancers including LSCC (lung squamous cell carcinoma) and HNSCC, was highly up regulated in response to arecoline treatment." (PMID 34316331, 2021).
myocardial ischemia (5 papers, 2019 to 2024). A disorder of cardiac function caused by insufficient blood flow to the muscle tissue of the heart. "Next to the profiling of Neat1 expression during cardiac ischemia, we studied the effects of a genetic Neat1 loss in a murine setting of MI." (PMID 31634682, 2019). "This study aimed to investigate the effect of long non-coding RNA nuclear enriched abundant transcript 1 (lnc-NEAT1) on cell proliferation and apoptosis in myocardial ischemia/reperfusion (I/R) injury cells, and explore its target miRNAs." (PMID 31390999, 2019).